IL1B (interleukin 1 beta)
Diseases named in the same sentence as IL1B in open-access papers (continued):
Sharing a sentence is not in itself a finding about the gene and the disease.
diabetes (continued). "The levels of cytokines (e.g., IL-6, IL-1β, IL-10, and IL-12) and chemokines (e.g., MCP-1, MIG, and RANTES) are perturbed in MDMs derived from patients with diabetes, both before infection and in response to Mtb infection." (PMID 29513874, 2018). "Blood glucose, incidence of diabetes, body weight, pancreatic histopathology, the amounts of CD4+T cell subsets, IL-1β level in serum and pancreatic expressions levels of HMGB1, and NF-κB p65 protein were analyzed." (PMID 30410469, 2018). "Results exhibited that higher mRNA levels of CRP, IL-6, IL-1β, and TNF-α in diabetes rats were obviously reduced after the treatment with STX for 7 weeks." (PMID 30210342, 2018). "Inhibition of pJNK1 decreases diabetes-induced serum NO levels, Fmo3 and ICAM expression in the liver, IL-1β production in Kupffer cells, and ICAM expression in the aorta." (PMID 29851956, 2018). "The CS-ZPV-treated groups at doses 1 and 2 had lower levels of IL-1β and TNF-α cytokines at 7 and 14 days than those the untreated diabetes group." (PMID 30670966, 2018). "In previous studies, cataract surgery may induce the elevation of vascular endothelial growth factor, monocyte chemotactic protein-1, interleukin-1β (IL-1β), and IL-6 in the aqueous fluid of patients with and without diabetes by causing changes to the blood–retinal barrier." (PMID 30133506, 2018). "The current study shows that Lf decreased diabetes-induced inflammation by inhibiting the TLR-4-NF-κB axis with subsequent reduction in serum proinflammatory cytokines; IL-1β, IL-6, and IL-18, in diabetic children." (PMID 30534206, 2018). "PIO significantly attenuated the diabetes-induced activation of the NLRP3 inflammasomes and their downstream effectors, including caspase-1, IL-1β, and IL-18." (PMID 28708885, 2017). "Since NLRP3 inflammasome regulates inflammatory pathways in diabetes, we examined serum amyloid A (SAA), a major prototypic marker of inflammation in rodents, as well as circulating levels of IL-1β and IL-18." (PMID 29435463, 2017). "During the progression of diabetes, CB1 promotes the Nlrp3-ASC inflammasome activation and the release of IL-1β and IL-18 in infiltrating macrophages, which act as paracrine signals to induce beta cell apoptosis." (PMID 29033935, 2017). "Before treatment with melatonin, levels of IL-1β, IL-6 and PGE2 in gingival crevicular fluid of patients with diabetes and perio-dontal disease were significantly higher than in healthy control subjects without periodontitis." (PMID 29075409, 2017). "To further investigate protein expression and tissue localization of Il-1β and galectin-1 in the retina of mice with STZ-induced diabetes, we performed double-staining immunofluorescence." (PMID 29170525, 2017). "Western blotting analysis demonstrated a significant increase in the amount of immunoreactive peptide corresponding to gene expression of IL-1β, IL-6, and TGF-β1 in renal tissue from group with diabetes compared to the control group (resp)." (PMID 26955430, 2016). "SASP genes (i.e., IL-1α, IL-1β, IL-6, and TNF-α) are chronically activated in cells and tissues from diabetes patients." (PMID 27340505, 2016). "In this study, we have shown that diabetes enhances the increase in HMGB1 serum levels and expression of the inflammatory cytokines IL-1β, IL-6, and inflammation-related enzyme after cerebral I/R injury in mice." (PMID 27596007, 2016). "This contrasts with previous findings in C57Bl/6 mice at later time points after 8 weeks of diabetes, in which we were able to detect increased ICAM-1 mRNA in retinal vessels and enhanced levels of TNFα, IL-6, and IL-1β mRNA in whole-retina homogenates." (PMID 25918731, 2015). "Subgroup analyses of the gene expression of Homer1, Homer2, Homer3, IL-1β, and TNF-α between CAD patients and controls by hypertension and diabetes." (PMID 25551602, 2014). "The gene expression of Homer1, Homer2, Homer3, IL-1β, and TNF-α were analyzed by hypertension and diabetes between CAD patients and controls." (PMID 25551602, 2014).
diabetes (continued). "The levels of inflammatory mediators (NF-kB, IL-1β, tumor necrosis factor α, and ICAM-1 etc.)are elevated in the retina in diabetes and leukostasis is increased." (PMID 24479616, 2014). "Puerarin at 20 and 100 nM decreased the diabetes-induced elevation of TNF-α, IL-1β, and IL-6 (P < 0.001) and NF-κB DNA binding activities (P < 0.01 and P < 0.001 at 20 nM and 100 nM, resp.)." (PMID 25089076, 2014). "We found that diabetes enhances the production of O2−, activates caspase-3, and induces the expression of proinflammatory cytokines (TNF-α and IL-1β) in the brain." (PMID 24739976, 2014). "The enhanced pro-inflammatory burden in diabetic mice is also reflected by the overall increased levels of circulating plasma cytokines (IL-6, IFN-γ, IL-12p70, IL-1β, IL-10, TNFα, OPN and sVCAM-1) after 8 weeks of diabetes." (PMID 23755169, 2014). "For IL-1β and TNF-α, there were significant differences between CAD patients and controls in participants of hypertension (p < 0.001 and p < 0.001), diabetes (p = 0.017 and p = 0.025), respectively." (PMID 25551602, 2014). "Thus given inflammasome activation can impair several metabolically relevant signaling proteins such as Sirt1, additional studies are required to test whether specific inflammasome or caspase-1 inhibitors offer better therapeutic alternatives than IL-1β inhibition as treatment for diabetes." (PMID 23483669, 2013). "IL-1α and IL-1β protein levels were significantly reduced in lumbar DRG and in sciatic nerve at 2 and 5 months of diabetes (*p<0.05 vs diabetic)." (PMID 24152426, 2013). "Increased levels of pro-inflammatory cytokines MCP-1, IL-1β, IL-6, IL-18 and TNF-α have been reported in diabetes." (PMID 24359406, 2013). "Since elevated IL-1β, IL-6, and TNF-α were referred to as independent predictors of diabetes, decreased concentrations reveal the antidiabetic properties of functional food." (PMID 23690866, 2013). "In the diabetic mice, we observed aberrant and significantly elevated levels of IL-1α, IL-1β, IL-6 and CXCL10 compared to the control group, which indicated prolonged proinflammatory conditions during diabetes." (PMID 23533683, 2013). "Our findings of IL-1β upregulation by the PKC agonist PMA and prevention of the HG-induced IL-1β upregulation in BREC by calphostin C point to upregulation of IL-1β as a potential link between PKC activation and vascular dysfunction in diabetes." (PMID 22615852, 2012). "In this study, we further support our previous findings by showing that the expressions of TXNIP, pro-inflammatory IL-1β, iNOS, and pattern recognition receptors TLR4 and P2X7R in the retina are elevated at 4 weeks of diabetes." (PMID 22474421, 2012). "The NLRP3 inflammasome activation and subsequent maturation and secretion of IL-1β and IL-18 initiated further pro-inflammatory events, producing kidney damage of STZ-induced diabetic rats." (PMID 22701621, 2012). "Retinal plasma extravasation, leukostasis and mRNA levels of B1R, iNOS, COX-2, VEGF receptor type 2, IL-1β and HIF-1α were significantly increased in diabetic retinae compared to control rats." (PMID 22470485, 2012). "Immunohistochemical procedures for MMP-2, MMP-9, TNF-α, IL-1β, IL-6, RANKL, and RAGE were performed in rats after 1, 3, 6, 9, and 12 months of diabetes induction." (PMID 22611374, 2012). "it was demonstrated that diabetes increased proinflammatory cytokines including TNF-α, IL-1β and IL-6 in the circulating, renal production, and urinary excretion." (PMID 21699681, 2011). "Several well-known markers of inflammation secreted by the adipose tissue, including IL-6 (which stimulated the hepatic synthesis of CRP), IL-1β and TNF-α, have been referred as independent predictors of diabetes." (PMID 20652060, 2010).
diabetes (continued). "Klotho, which mitigates diabetes-induced elevation of serum creatine kinase-muscle/brain (CK-MB) and LDH, cardiac fibrosis, cardiomyocyte apoptosis, and cardiac dysfunction, also inhibits NLRP3 activation and TNF-α, IL-1β, and IL-18 expression." (PMID 41399377, 2026). "Diabetes worsens periodontitis via ↑ inflammatory response, impaired bone metabolism, oxidative stress, and AGE–RAGE signaling; GLP‐1RAs inhibit NF‐κB and activate AMPK, suppressing IL‐6, IL‐1β, and TNF‐α." (PMID 41328144, 2025). "The results showed that the levels of IL‐1β and TNF‐α in the serum samples obtained from the experimental groups increased in the diabetes group, and there was a significant decrease in both the 18β group and the silver nanoparticle‐loaded 18β group as compared to the diabetes group." (PMID 41280745, 2025). "Circulating IL-6 and IL-1β levels are elevated in individuals with type 1 diabetes compared with those without diabetes, with higher IL-1β levels in early-stages and with worse management." (PMID 40553147, 2025). "In diabetes, persistent hyperglycemia leads to “a state of chronic low-grade inflammation, characterized by elevated levels of pro-inflammatory cytokines such as tumor necrosis factor-alpha (TNF-α), interleukin-1 beta (IL-1β), and IL-6." (PMID 39139325, 2024). "Accordingly, we hypothesized that NLRP3 dysregulation might affect pyroptosis in diabetic ED and evaluated pyroptosis markers (GSDMD, GSDMD-N, pro-caspase-1, cleaved-caspase-1, ASC, IL-1β, and IL-18)." (PMID 39014129, 2024). "It has also been shown that among patients with peri-implantitis, salivary IL-1β, and IL-6 levels were significantly higher in those with diabetes than in those without diabetes." (PMID 38614881, 2024). "Moreover, it inhibited diabetes-induced neuroinflammation by decreasing the inflammatory markers NfκB, TNF-α, IL-1β, and IL-6 and downregulating the BDNF/ERK/CREP pathway." (PMID 38105928, 2023). "Data supporting diabetes-induced microglial phenotype in db/db mice include IL-1β and TNF-α upregulation in the cortex and hippocampus of these mice; as well as higher secretion levels of IL-1β, IL-6, TNF-α and MCP-1 by isolated forebrain mononuclear cells." (PMID 36869375, 2023). "Third, DAPA modulated systemic inflammation via regulation of the inflammatory mediators, including G-CSF, GM-CSF, IL-1β, and IL-17A in the LPS-treated rats with and without diabetes." (PMID 37376131, 2023). "It was reported that children with one or two diabetes-related antibodies (IA-2 and/or GAD65) have significantly higher levels of IL-1β and IL-2 and lower levels of IL-4 than children with diabetes who were negative for these markers." (PMID 37893217, 2023). "In addition, the promoting effects of the miR-30e-5p inhibitor on IL-1β and IL-18 expression were dramatically reversed by ELAVL1 knockdown in the BMSC-exo-treated diabetes model cells." (PMID 36794663, 2023). "The main contribution of this research was that diabetes enhances the lung injury and inflammation in rats due to elevated levels of TNF-α, IL-6, and IL-1β and lower levels of IL-10, lower SOD and GPx activity, TAC levels, and increased MDA and NO levels in tissue and BALF." (PMID 37520024, 2023). "Diabetes induced a significant increase in gene expression for Il1β and Il6 compared to ND mice, regardless of genotype." (PMID 37033925, 2023). "In addition, IL-1β increases the expression of PGE2, and TNF-α leads to insulin resistance and the accumulation of AGEs, exacerbating diabetes." (PMID 37374121, 2023). "Studies have shown that IL-1β-induced pancreatic β cell death and HMGB1 release may lead to the onset of diabetes." (PMID 37065747, 2023). "In terms of biochemical parameters, serum pentosidine showed a negative trend towards a longer duration of diabetes, whereas sRAGE-Pentosidine ratio and IL-1β showed a positive trend." (PMID 36759556, 2023).
diabetes (continued). "We found that diabetes induced strong increases in pancreatic IL-1β and TNF-α, but not IFN-γ, at the protein level at the 4-week time point, and all cytokines were further elevated at the 8-week time point." (PMID 37040355, 2023). "Though we found negative correlations between fasting C-peptide and IL-1β, IL-2Rα, and IL-16 concentrations, it should be emphasized that the majority of patients in our study had long-term diabetes with undetectable beta-cell function." (PMID 37893217, 2023). "Additionally, experimental studies have demonstrated that rodents with diabetes have reduced levels of microRNA-146a, and its dysregulation seems to occur with stimuli such as increased NF-κB, TNF-α, and IL-1β expression." (PMID 37585913, 2023). "Subgroup analysis showed that sex, hypertension, hyperlipidemia, diabetes, smoking,anddrinking did not affect Malat1 expression, IL-1β, and VitD in peripheral blood ofischemic strokepatients (Table-3)." (PMID 38974129, 2023). "OA cartilage explants from diabetes mellitus patients had an increased responsiveness to Il-1B induced inflammation, compared to age and BMI matched non-diabetic controls." (PMID 37520829, 2023). "Subsequently, MIN6 cells were treated with a cytokine mixture of TNF-α, IL-1β and IFN-γ in the presence or absence of UC, and verapamil, a TXNIP inhibitor for prevention of beta cell loss and diabetes development, was used as a positive control in this study." (PMID 38040681, 2023). "In addition, mRNA expressions of inflammatory markers IL-1β and TNF-α were negatively correlated with protein levels of LC3B-II and positively correlated with SQSTM1 in PBMCs from type 2 diabetes mellitus patients." (PMID 36994103, 2023). "Diabetes not only impairs antioxidant integrity but also initiates neuroinflammatory reactions by activating the nuclear transcription factor NfκB, which stimulates IL6, IL-1β, and TNF-α pro-inflammatory cytokines." (PMID 38105928, 2023). "More specifically, the previous database of human samples from obese patients with diabetes showed that IL-1β was dramatically upregulated compared with obese non-diabetic subjects." (PMID 38062308, 2023). "Both the activated and resting states of neutrophils from patients with diabetes exhibit an extremely increased secretion of tumor necrosis factor (TNF)-α, interleukin (IL)-8, and IL-1β, and elevated levels of inflammatory cytokines are associated with increased susceptibility to pathogens." (PMID 36079032, 2022). "For example, mitochondrial dysfunctions have been unraveled in various autoimmune diseases, such as RA, SLE, and diabetes, while the expression of pro-inflammatory cytokines such as TNF-α, IL-6, and IL-1β is upregulated in the adipose tissues of obese and diabetic subjects." (PMID 35997820, 2022). "Furthermore, scRNA-Seq analysis enriched a subcluster of activated microglia named cluster 36 with an increased number and majority of IL-1β and Tnf expression in STZ-induced diabetic retina." (PMID 36119084, 2022). "Recently, the CANTOS trial showed that targeting IL-1β reduced ASCVD event rates in patients with diabetes without lowering lipids or blood pressure." (PMID 35631132, 2022). "Interestingly, the effects of diabetes on cystitis are at least partially contributable to the increases in NLRP3, a regulator for IL-1β." (PMID 36405726, 2022). "In addition, the expressions of pro-inflammatory factors (IL-1β and TNF-α) are downregulated by overexpressing miR-20b-3p in the diabetic retina." (PMID 36292956, 2022). "Besides, the M1 polarization markers, including IL-1β, IL-6 and TNF-α increased in the isolated retinal microglia from diabetes rats, with the decreasing M2 polarization markers such as IL-4, IL-10 and TGF-β." (PMID 35300330, 2022). "In diabetes, the activation of NF-κB stimulates the transcription of NLRP3 and activation of the NLRP3 inflammasome, resulting in the cleavage of caspase-1, which increases the production of mature IL-1β and IL-18." (PMID 34997266, 2022).
diabetes (continued). "Chronic inflammation is an important pathophysiological factor leading to diabetes, which is manifested by higher levels of Nod-like receptor protein 3 (NLRP3), Caspase-1, Interleukin-1β (IL-1β), and various antiviral inflammatory cytokines, inducing a strong inflammatory response in the body." (PMID 36248820, 2022). "In addition, Lcn10-KO macrophages exhibit higher expression of cytokines/chemokines (i.e., IL-6, IL-1β, and CCL2) than wild-type controls, which are also major culprits for the development of cardiomyopathy during diabetes." (PMID 35757735, 2022). "Our results uncovered that AS-IV can protect retinal cells against diabetes induced retinopathy, which may act on target proteins AKT1, CASP3 and HIF1α, VEGFA, IL6, IL1β, SRC and CTNNB1, and might be involved in the regulation of PI3K-AKT signaling pathway." (PMID 35814228, 2022). "Os níveis séricos de IL1-β e TNF-α aumentaram significativamente no grupo diabético em comparação com o grupo controle nos dias 14 e 28 após a indução do diabetes (p<0,05) ( Tabelas 4 e 5 )." (PMID 34709299, 2021). "Different phase 1 and 2 clinical trials in diabetic patients of recent onset showed that anti-IL-1b agents are safe but are not efficacious as single agents for diabetes control." (PMID 34202017, 2021). "Diabetes and hypertension lead to structural and functional changes of the neurovascular unit, alter collaterals, and elevate MMP-9, ROS, and proinflammatory cytokines (TNF, IL-1β, and IL-6)." (PMID 34054705, 2021). "Conversely again, the levels of induction of IL-6, IL-1β, and MCP-1 caused by “diabetes-like” conditions in presence of the non-phosphorylatable (148A) mutant were comparable to those obtained in the absence of HspB4/αA-crystallin (EV)." (PMID 34071438, 2021). "One patient with virus-negative inflammatory cardiomyopathy and decompensated type 2 diabetes mellitus was treated with high-dose immunoglobulin and then with IL-1β inhibitor (anakinra) with improvement of ventricular function." (PMID 33355356, 2021). "The diabetes-induced HMGB1 shuttling from the nucleus with subsequent activation was triggered mainly by the persistent hyperglycemia and the inflammatory agents, such as IL-1β and TNF-α." (PMID 33915770, 2021). "This is in line with data from NOD mouse studies of IL-1 receptor- or IL-1β-deficient NOD mice, where no protection from diabetes development was observed." (PMID 35156097, 2021). "Studies have demonstrated that activation of neutrophils and macrophage results to oxidative stress as well as inflammatory cytokines release including IL-1β, IL-6 and TNF-α, leading to the decrease of insulin secretion, hepatic steatosis and a series of metabolic disorders in diabetes." (PMID 32028957, 2020). "In this study, we investigated the analgesic effect of the combination of B1/B6/B12 (VBC) and its effects on the expression of P2X3 and TRPV1 receptors in DRG neurons and the inflammatory cytokines IL-1β, TNF-α, and NGF in the spinal cord in STZ-induced diabetic rats." (PMID 32104520, 2020). "The presence of Porphyromonas gingivalis in the periodontal pockets affects the glycemic index in diabetes, and the periodontitis-inducing cytokines TNF-α, IL-6 and IL-1β are also insulin antagonists, triggering irreversible changes in the body's immune response and inflammatory state." (PMID 32634783, 2020). "To further unveil the regenerative potential of PIAA under pathophysiological conditions, we treated INS-1 832/13 cells with a cytokine mix containing IL-1β, IFN-γ, and TNF-α, which are released by inflammatory immune cells and contribute to increased β-cell apoptosis during diabetes progression." (PMID 33168920, 2020). "Immediately after diabetes manifestation, antibody combination therapies were initiated over 5 days with anti-TNF-α (tumour necrosis factor), anti-IL-1β (interleukin), or anti-IFN-γ (interferon) together with anti-TCR for the reversal of the diabetic metabolic state in the IDDM rat." (PMID 32607871, 2020).